HGF (hepatocyte growth factor)
Diseases named in the same sentence as HGF in open-access papers (continued):
Sharing a sentence is not in itself a finding about the gene and the disease.
cancer (continued). "Matriptase is an 80 kDa serine protease involved in cancer metastasis by the activation of urokinase-type plasminogen activator (u-PA) and hepatocyte growth factor." (PMID 17971775, 2007). "This strengthens the link between nucleolin and HGF function, at the same time that it argues for cell surface localization of the nucleolin protein during cancer progression." (PMID 16869958, 2006). "Together, there is now clear evidence of nucleolin's involvement in cancer cell behavior and response to HGF, although this protein's direct and/or indirect functions remain to be discovered." (PMID 16869958, 2006). "Although further studies are necessary to clarify these mechanisms, these studies on the HGF/c-Met pathway will aid the development of new therapeutic strategies for the treatment of NSCLC cancer patients." (PMID 15083185, 2004). "HGF expression was found in 60% (9 of 15) of adenocarcinoma samples and the intensity of staining was similar to that observed in the liver tissue of malignant tumor patients." (PMID 14960204, 2004). "In all, 22 carcinomas (25.0%) were intratumoral HGF-positive, 14 carcinomas (15.9%) were stromal HGF-positive, and 36 carcinomas (40.9%) were intratumoral c-Met-positive." (PMID 15083185, 2004). "Hepatocyte growth factor/scatter factor (HGF/SF) is a multifunctional factor involved both in development and tissue repair, as well as pathological processes such as cancer and metastasis." (PMID 11027427, 2000). "Hepatocyte growth factor (HGF) is a stromal cell-derived cytokine that can stimulate matrix invasion by carcinoma cells." (PMID 10574262, 1999). "The content of HGF in cancer tissue was also significantly higher than that in normal mucosa, and it was correlated with the serum HGF concentration for the peripheral venous blood." (PMID 9716026, 1998). "By interfering with the HGF/Met interaction, these compounds may attenuate downstream signaling pathways involved in cancer cell proliferation and metastasis." (PMID 40333783, 2025). "In addition, it was also reported that the pharmacological effect of MET inhibitors on the growth of cancer cells was attenuated under HGF-rich condition, and additional inhibition of inhibitor of HGF-activating proteases overcame the resistance." (PMID 40299447, 2025). "Paradoxically, the N375S mutant exhibits decreased binding to HGF, instead conferring enhanced ligand-independent binding affinity to HER2; cancers with this mutation are insensitive to MET TKI treatment but may respond well to HER2-targeted therapy." (PMID 39858062, 2025). "We believe that this newly identified c‐Met ligand, B7‐H3, is of potential importance as HGF transcripts expression in cancer tissues are lower than that of the corresponding normal tissues, and HGF protein levels are not significantly correlated with patient survival (data from GEPIA)." (PMID 40859957, 2025). "Taken together, STMN1, HGF, and MET overexpression are associated with cancer progression." (PMID 40723207, 2025). "Activation of the HGF/MET signaling axis is known to correlate with cancer progression." (PMID 40299443, 2025). "In cancer tissue, upregulation of the HGF/MET signaling axis occurs mainly in a paracrine fashion." (PMID 40299447, 2025). "On the other hand, hepatocyte growth factor (HGF), produced by cancer-associated fibroblasts (CAFs) and mesenchymal stromal cells (MSCs), triggers the mesenchymal-epithelial transition (c-MET) receptor tyrosine kinase (RTK) predominantly found on c-MET+ cancer cells and MDSCs." (PMID 40281554, 2025). "Similarly, the kinase inhibitor Merestinib targets the tyrosine kinase receptor MET (hepatocyte growth factor) and is being investigated as a potential anti-cancer therapy candidate." (PMID 41011176, 2025).
cancer (continued). "This central role is largely attributed to aberrant c-MET/HGF signaling, which derives epithelial-to-mesenchymal transition, enhances cancer cell migration and invasion, stimulates angiogenesis through VEGF cross-talk, and contributes to chemoresistance, hallmarks frequently observed in TNBC." (PMID 41289612, 2025). "Overall, the mechanisms that regulate CCL2 and HGF appear distinct and multi-factorial and could depend on the cancer type." (PMID 40736024, 2025). "Notably, studies indicate that upon the addition and interaction of HGF with CD44v6 expressing cancer cells, there is an increase in the number of CD44-HGF-bound dimers and in the diffusion coefficient in the plasma membrane of such complexes." (PMID 40114966, 2025). "They secrete TGF-β, leukemia inhibitory factor (LIF), growth arrest-specific protein 6 (GAS6), fibroblast growth factor 5 (FGF5), growth differentiation factor 15 (GDF15), and hepatocyte growth factor (HGF), which drive the invasive and proliferative behaviors in cancer cells." (PMID 40313969, 2025). "In CRLM, heparan sulfate proteoglycans, such as syndecan-1 and glypican-3, facilitate cancer cell proliferation and metastasis by sequestering growth factors like hepatocyte growth factor (HGF) and fibroblast growth factor (FGF), which activate pro-tumorigenic pathways." (PMID 40149289, 2025). "Consequently, inhibitors targeting the HGF/Met signaling pathway have emerged as promising candidates for cancer therapy." (PMID 40333783, 2025). "To this end, we hypothesized that the binding of cytokines TGF-β1, IL-6, and HGF to their respective receptors induces cancer cells to adopt a mesenchymal metastatic phenotype through the Neu-1-MMP9-GPCR crosstalk signaling platform." (PMID 40227834, 2025). "Additionally, activation of HGF/c-MET signaling has been shown to enhance the cancer stem cell properties of NSCLC." (PMID 39201787, 2024). "Thus, inhibition of the HGF/MET axis occurring on cancer cells and TME components will revert stroma activation." (PMID 38892318, 2024). "Notably, cell adhesion proteins (Ceacam family) and hepatocyte growth factor (HGF/SF) are the critical modulators of cancer progression, particularly during metastasis." (PMID 39227808, 2024). "In particular, sEVs from HCC were shown to induce sorafenib (TKI) resistance in vitro by activating hepatocyte growth factor/mesenchymal- epithelial transition factor/AKT (HGF/c-Met/Akt) signaling in other HCC cancer cells, thus preventing sorafenib-induced apoptosis." (PMID 38339318, 2024). "Studies have reported that pairing the Met receptor aptamer with a cancer cell biomarker, CD71 or Transferrin receptor (TfR), using a bispecific aptamer interferes with the interaction between the Met receptor and hepatocyte growth factor (HGF), thereby inhibiting cancer cell metastasis." (PMID 39407665, 2024). "The mechanism may be due to the limited activation of the paracrine signaling pathways caused by low secretion of HGF and EGF7 from CAFs, and these signaling pathways (e.g., PI3K/Akt, MAPK signaling) contribute to cancer proliferation and antiapoptosis." (PMID 38643164, 2024). "In addition, the upregulated paracrine HGF binds to the c-MET receptor on migrating cancer cells, providing fertile "soil" for "seeds" and promoting the landing and proliferation of metastatic cancer cells." (PMID 38992695, 2024). "Increased MET and HGF levels have been reported in various human cancers." (PMID 39519229, 2024). "Met and its ligand HGF are crucial to the signaling pathways that participate in various essential cellular events such as cell proliferation, invasion, angiogenesis, and the regulation of cancer stem cells." (PMID 39130630, 2024). "Our study also found that low level of serum HGF might be a good prognostic factor for cancer patients receiving ICIs-based systemic therapy." (PMID 38776028, 2024). "Therefore, the activated HGF/c-MET pathway is considered as a negative regulator for cancer immunotherapy." (PMID 38776028, 2024).
cancer (continued). "Evidence from previous studies showed that HGF-induced VEGF expression in different cancer cells." (PMID 39302921, 2024). "Notably, activation of the HGF/c-Met signaling pathway can upregulate glycolysis, resulting in increased lactate secretion from cancer cells." (PMID 39201787, 2024). "HGF/c-Met is already a very promising target for cancer therapy." (PMID 39418248, 2024). "Finally, since our studies included only cancer cells, we show that autocrine signaling by HGF—a widely recognized paracrine growth factor—can be a potent inducer of cetuximab-resistant phenotype." (PMID 38212428, 2024). "Additionally, the binding of HGF to the c-MET receptor on cancer cells triggers a cascade of downstream signaling events that further induces the production of uPA." (PMID 38473413, 2024). "Moreover, our IHC data revealed that MET+ cancer epithelial cells were closely surrounded by HGF+ fibroblasts, indicating potential communication through the MET‐HGF signalling pathway." (PMID 38445456, 2024). "Consequently, c-MET and HGF have emerged as prominent targets for molecularly targeted cancer therapies." (PMID 39335535, 2024). "HGF/c-Met activation may induce the dedifferentiation of common adenocarcinoma cells, which revert to a stem cancer cell phenotype and produce AFP or hepatoid differentiation." (PMID 38817451, 2024). "A specific treatment targeting the HGF/cMET pathway in XP-C patients could prevent the development of aggressive carcinomas, as is already being applied in individuals from the general population." (PMID 39409898, 2024). "The HGF/c-Met pathway is crucial in the crosstalk between cancer and stromal cells in the TME." (PMID 37686233, 2023). "HGF has been shown to induce migration and invasion in different cancer types." (PMID 36765641, 2023). "HGF acts on its receptor, c-Met, on the hepatocytes, promoting several processes including cell division; motility; intracellular invasion; and the development of cancer." (PMID 37509493, 2023). "The HGF/c-MET signaling pathway is rarely activated in adults except in cancer." (PMID 36789987, 2023). "Thus, proper paracrine MET activation takes place in the human cancer cells transplanted into these animals, allowing us to fully estimate the contribution of the HGF-MET axis to the cell-autonomous functions involved in the metastatic process." (PMID 37345079, 2023). "In addition, aberrant HGF/c-Met upregulation and activation were found to be frequently observed in BCa and correlated with cancer progression and invasion." (PMID 36959792, 2023). "As MET dependency has considerably affected the success and failure of MET-targeted clinical trials, additional studies are required to understand the role of MET Ser1016 phosphorylation in HGF-dependent cancers or cancers with lower levels of MET amplification." (PMID 37188738, 2023). "Pro-cancer factors, e.g. hypoxia inducible factors 1α (HIF1α) and hepatocyte growth factor (HGF) or anti-cancer factors like tissue inhibitor of metalloproteinase 2 (TIMP-2) have been associated with cancer aggressiveness or metastasis in experimental models of cancer progression." (PMID 35953652, 2023). "Moreover, the detection of HGF in cancer cells is consistent with its requirement for METex14 activation, signalling and oncogenity, as observed in our cell lines." (PMID 36799689, 2023). "From a functional point of view, HGF stimulation of MET−/− cancer cells was ineffective in eliciting intracellular signaling and in sustaining biological functions predictive of malignancy in vitro (i.e., anchorage-independent growth, invasion, and survival in the absence of matrix adhesion)." (PMID 37345079, 2023). "Regarding HGF, there is considerable debate whether the cancer cells secrete this growth factor or if this is done by stromal cells such as fibroblasts." (PMID 36053327, 2023).
cancer (continued). "Capmatinib is an ATP-competitive and highly selective small molecule c-MET receptor TKI that demonstrated inhibition of MET activation in cancer cells whose growth is driven by MET amplification, MET overexpression, MET exon 14 skipping mutations, and HGF-mediated activation." (PMID 38269272, 2023). "Pan-cancer analysis revealed different prognostic value of HGF expression in various cancer types." (PMID 37828456, 2023). "The expression and roles of chemokines and their receptors in malignant neoplasms can also be regulated by various microenvironmental factors, including chronic inflammation, hypoxia, hepatocyte growth factor (HGF), and vascular endothelial growth factor (VEGF)." (PMID 36983949, 2023). "In the context of cancer, abnormal HGF secretion and activation, in conjunction with MET gene mutations that are closely associated with overexpression, amplification, and selective splicing, lead to the aberrant activation of the HGF/c-MET axis." (PMID 37919751, 2023). "Therefore, targeting the HGF/C-MET axis or the Hh pathway alone as a strategy to combat cancer stemness and drug resistance appears to be insufficient." (PMID 37919751, 2023). "MET/HGF-SF signaling could impact the ability of T cells to respond competently to cancer cells, by reducing the DCs’ capacity to present antigens and recruiting immunosuppressive cells." (PMID 37842234, 2023). "HGF, HMOX1, ELN, and GREM1 genes associate with stromal fibrosis and contribute to malignancy through the proliferation of cancer-associated fibroblasts (CAFs) in various kinds of cancers." (PMID 37240308, 2023). "Also, in various solid tumors, HGF and IL-6 play key roles in the phenotype modulation of cancer cells." (PMID 35986321, 2022). "Dysregulation of HGF-mediated signaling results in multiple deadly cancers." (PMID 35778602, 2022). "Validated phosphotyrosine‐mimetic fragments F1, F2, and F4 were incorporated into the pyrazolone scaffold of the SHP2‐specific inhibitor GS493 and yielded nanomolar inhibitors of SHP2 that were able to block the Raf‐Erk‐Map signaling pathway in HGF‐activated cancer cells." (PMID 35781901, 2022). "Although diverse pathways might affect EMT, activation of the HGF/c-Met pathway has been found to play a prominent role in the regulation of the EMT program in diverse cancers." (PMID 36291760, 2022). "Furthermore, peritumoral neutrophils represent a source of hepatocyte growth factor (HGF) and IL-17A, which promote cell division and cancer progression." (PMID 36551635, 2022). "Interestingly, the amount of HGF detected in the vem + pic group (11.4 ± 0.9 pg mL−1) significantly decreased by the cancer‐inhibiting effect of the BRAF/PI3K inhibitor." (PMID 36026581, 2022). "The activated MET/HGF pathway promotes EMT in several types of cancers." (PMID 35773658, 2022). "Currently, there is a large body of literature linking the HGF/c-MET pathway to cancer." (PMID 36034555, 2022). "In addition, scratch-wound and transwell migration assays showed that TGFβ, HGF, or both markedly increased cancer cell migration and invasion, and these effects were abolished by crizotinib." (PMID 35999455, 2022). "Therefore, the c-MET receptor tyrosine kinase and HGF have been identified as potential targets for cancer therapeutics and recent years have seen a race to synthesize molecules to block their expression and function." (PMID 36034555, 2022). "The HGF/MET complex has been reported to signal migration and/or differentiation of neural crest cell-derived structures, via overexpression, amplification, aberrant splicing, or mutations, associated with many cancer types." (PMID 36471782, 2022). "Multiple pre-clinical studies reviewed above suggest that the HGF/c-MET pathway is important for protecting cancer cells from insult, and so it follows that anti-HGF/c-MET therapy could be effective as an adjuvant to other cytotoxic therapies." (PMID 36034555, 2022).
cancer (continued). "Experimental models have shown that adipokines such as leptin and hepatocyte growth factor may regulate cancer cell proliferation and invasiveness." (PMID 36249201, 2022). "In OC, CAFs stimulate cancer invasiveness and chemo-resistance through the secretion of hepatocyte growth factor (HGF), glucose-regulated protein 78 (GRP78), and the activation of hepatocyte growth factor receptor HGFR (also known as cMet)/PI3K/AKT signaling pathway." (PMID 35269636, 2022). "Other cells involved in the niche region and are affected by CSCs include cancer-associated fibroblasts (CAFs), which are known to increase proliferation, enhance ECM production and secret essential factors such as CXCL12, VEGF, PDGF, and HGF." (PMID 35659296, 2022). "C7 can act as an anti-cancer gene to inhibit HCC metastasis by targeting the HGF signaling pathway." (PMID 36307751, 2022). "In addition, HGF is involved in cancer cell metastasis by regulating the expression of several proteins through modulating cell-to-cell junction stability." (PMID 35630066, 2022). "Inhibition of HGF/c-Met blocked circCCDC66-induced enrichment of cancer stem cells." (PMID 36698408, 2022). "Accordingly, HGF/c-Met signaling has been a prominent molecular target for cancer therapy." (PMID 35851277, 2022). "Moreover, HGF promotes cancer cell metastasis by controlling focal adhesions by modifying the expression of many proteins." (PMID 35630066, 2022). "Drugs that target c-MET may offer a new strategy for the control of aggressive cancers and the combination of HGF/MET inhibitors with conventional chemotherapy in patients affected by different cancer types has shown promising results." (PMID 35480115, 2022). "As mesenchymal cells are known to be a predominant source of HGF production, the membranous expression of HGF in cancer cells assessed in this study might represent a paracrine effect on the membrane receptor (i.e., c-Met)." (PMID 35205843, 2022). "Our study provides evidence that cellular senescence inhibits cell competition-mediated elimination of oncogenic cells through HGF signaling, suggesting that it may lead to cancer incidence during aging." (PMID 35851277, 2022). "In the present study, to assess the biological significance of activating the HGF/c-Met signaling pathway in the crosstalk between nerves and cancer cells, a cancer cell-DRG (dorsal root ganglion) coculture system was established, and cancer migration toward DRG and neurite outgrowth was measured." (PMID 35449152, 2022). "However, CDCP1’s requirement for HGF-induced invasion and metastasis of human cancer cells was undetermined." (PMID 35085554, 2022). "One of the key pathways that may mediate cancer-stromal interactions is the hepatocyte growth factor (HGF) and its receptor c-MET pathway." (PMID 36591282, 2022). "In addition to growth factors of the VEGF family, many other mediators have been implicated in promoting lymphangiogenesis in cancer, including PDGF-BB, FGF2, and HGF." (PMID 35504887, 2022). "Therefore, HGF creates a microenvironment through interaction between cancerous cells and adjacent stroma, increasing the further development and invasiveness of cancer." (PMID 35986321, 2022). "In addition, the molecular mechanism of HGF/c-Met is responsible for enhancing cancer cell invasion, proliferation, survival and morphogenesis via signaling pathways, such as PI3k/Akt, Ras/MAPK and JAK/STAT." (PMID 35568918, 2022). "Binding of HGF to its receptor MET stimulates cancer cells through the phosphorylation of the HGF/MET signaling pathway, leading to downstream activation of multiple cytokines implicated in cellular motility, proliferation, angiogenesis, and invasive growth of cancer cells." (PMID 34997350, 2022). "Hepatocyte growth factor (HGF) binds to the c-mesenchymal-epithelial transition (c-Met) receptor to activate the downstream signaling pathway, and it plays an important role in the occurrence and development of various cancers." (PMID 35242498, 2022).